TMPRSS11E (transmembrane serine protease 11E)
Description:
Serine protease which possesses both gelatinolytic and caseinolytic activities. Shows a preference for Arg in the P1 position.
Synonyms: DESC1; TMPRSS11E2
Tractability: Small molecule: a structure with a bound ligand is known. Antibody: UniProt places it where antibodies can reach, with medium confidence; UniProt predicts a signal peptide or a membrane-spanning region; its Gene Ontology location is reachable by antibodies, with medium confidence.
Gene: Protein-coding gene on chromosome 4 (68,447,463 to 68,497,604, forward strand). Ensembl gene ENSG00000087128.
Subcellular location: Cell membrane; Secreted (Transmembrane protease serine 11E catalytic chain)
Subcellular location (Human Protein Atlas): Golgi apparatus; Predicted to be secreted
Gene Ontology:
Molecular function: protein binding; serine-type peptidase activity; serine-type endopeptidase activity
Biological process: cognition; protein processing; proteolysis
Cellular component: plasma membrane; extracellular region
Genetic constraint (gnomAD): Loss-of-function variants: 42 observed, 51.3 expected, observed/expected ratio (o/e) 0.82, 90% interval 0.64 to 1.06. The upper end of that interval is the gene's LOEUF score, 1.06, which puts it in group 4 of 6, group 1 being the genes least tolerant of losing a copy. Missense variants: 504 observed, 507.84 expected, observed/expected ratio (o/e) 0.99, 90% interval 0.92 to 1.07. Synonymous variants: 153 observed, 171.65 expected, observed/expected ratio (o/e) 0.89, 90% interval 0.78 to 1.02.
Homologues: Orthologues: chimpanzee TMPRSS11E (99% identical), macaque TMPRSS11E (95% identical), pig TMPRSS11E (82% identical), rabbit TMPRSS11E (78% identical), guinea pig TMPRSS11E (77% identical), mouse Tmprss11e (76% identical), rat Tmprss11e (75% identical), zebrafish st14a (29% identical), zebrafish st14b (28% identical), zebrafish tmprss15 (27% identical), Drosophila melanogaster Sb (23% identical), Drosophila melanogaster CG1632 (18% identical), and 2 more. Paralogues in human: TMPRSS11F (44% identical), TMPRSS11A (42% identical), TMPRSS11D (39% identical), TMPRSS11B (38% identical), ST14 (32% identical), TMPRSS6 (30% identical), TMPRSS13 (29% identical), TMPRSS3 (29% identical), TMPRSS9 (28% identical), TMPRSS2 (28% identical), TMPRSS7 (28% identical), HPN (27% identical), and 5 more.
Diseases named in the same sentence as TMPRSS11E in open-access papers:
TMPRSS11E is named in the same sentence as 18 diseases in open-access papers, as found by Europe PMC text mining. Sharing a sentence is not in itself a finding about the gene and the disease. The quoted sentences say what the papers report.
esophageal squamous cell carcinoma (6 papers, 2018 to 2024). Esophageal squamous cell carcinoma (ESCC) is a type of esophageal carcinoma (EC) that can affect any part of the esophagus, but is usually located in the upper or middle third. "DESC1 is a member of the type II transmembrane serine protease (also known as transmembrane protease, serine 11E; TMPRSS11E) and downregulated in squamous cell carcinoma of the head and neck and esophageal squamous cell carcinoma." (PMID 34064422, 2021).
colon cancer (2 papers, 2022 to 2024). "Immunohistochemical methods were used to compare the expression of PRGs (SLC2A3, TMPRSS11E, and UPK3b) in colon cancer and their expression in normal gastric tissues." (PMID 36246625, 2022). "In a recent study, functional analysis revealed a negative correlation between three genes (SLC2A3, TMPRSS11E, and UPK3B) can predict the overall survival of patients with colon cancer, finding that it is negatively correlated with the proliferation and migration of colon cancer cells." (PMID 39062587, 2024).
bladder cancer (1 paper, 2019). "And thirdly, we firstly identified a set of 4 genes (TMPRSS11E, SCEL, KRT78, TMEM185A) that were significantly associated with poor overall survival of bladder cancer patients, some of which have not been investigated in urinary bladder cancer before." (PMID 31737111, 2019).
psoriasis (1 paper, 2021). An autoimmune condition characterized by red, well-delineated plaques with silvery scales that are usually on the extensor surfaces and scalp. "Other transcripts such as Fbp1 are important in the Nrf2 stress pathway, Stra6 is involved in vitamin A transport in a murine psoriasis model, and 2 transmembrane proteases (Tmprss11e/f) are involved in skin barrier function." (PMID 34823472, 2021).
tumor (9 papers, 2007 to 2024). "UBE2S, HMMR, TMPRSS11E and KRT6A were found to be up-regulated in tumor tissues relative to surrounding non-cancerous and normal tissues in the screening cohort." (PMID 37199651, 2023).
cancer (5 papers, 2007 to 2025). A tumor composed of atypical neoplastic, often pleomorphic cells that invade other tissues. "TMPRSS11E, also known as DESC1, is a type II transmembrane serine protease that has been implicated in cancer progression." (PMID 41080752, 2025).
infection (3 papers, 2017 to 2025). The state of being infected such as from the introduction of a foreign agent such as serum, vaccine, antigenic substance or organism. "This study reveals the infection mechanisms of PDCoV in human-derived cells, highlighting the roles of CTSL, TMPRSS11E, and furin in viral entry and release." (PMID 40787987, 2025).
TMPRSS11E also shares sentences with these, for which no sentence is quoted: squamous cell carcinoma (3 papers); breast carcinoma (1); esophageal cancer (1); head and neck cancer (1); head and neck tumours (1); Influenza infection (1); lymph node metastasis (1); neurodegenerative disease (1); pulmonary disease (1); urinary bladder cancer (1); virus infection (1).